BRCA2 (BRCA2 DNA repair associated)
Diseases named in the same sentence as BRCA2 in open-access papers (continued):
Sharing a sentence is not in itself a finding about the gene and the disease.
peritoneal carcinoma (35 papers, 2007 to 2025). A peritoneum cancer that is located in the inside of the abdomen. "Female patients with BRCA1 or BRCA2 mutations are at an increased risk of ovarian, fallopian tube, and peritoneal cancers." (PMID 38910622, 2024). "JAMA Salpingo-oophorectomy and the risk of ovarian, fallopian tube and peritoneal cancers in women with a BRCA1 or BRCA2 mutation." (PMID 30636239, 2018). "The rucaparib/carboplatin combination had radiologic antitumour activity, primarily in BRCA1- or BRCA2-mutated breast and ovarian/peritoneal cancers." (PMID 28222073, 2017). "Sitzmann and Wiebke point to several important facts in one of the most recent metaanalyses evaluating, among other things, the frequency of occurrence of peritoneal cancer after salpingo-oophorectomy in patients with BRCA1/BRCA2 mutation." (PMID 26928677, 2016). "Women that carry germ-line mutations for BRCA1 or BRCA2 genes are at an increased risk of developing breast, ovarian and peritoneal cancer." (PMID 17850658, 2007). "Possibly, prolonged time to the diagnosis of peritoneal cancer might have been influenced by the inclusion of four patients with BRCA2 mutation into the study group of 32 patients." (PMID 30918533, 2019). "Peritoneal cancer was very rare among patients with BRCA2 mutation." (PMID 26928677, 2016). "The six most commonly recurring BRCA1 and BRCA2 mutations previously identified in a founder French Canadian population were investigated in 439 histologically defined ovarian, fallopian tube and primary peritoneal cancer cases that were ascertained at one hospital servicing French Canadians." (PMID 25884701, 2015). "This was supported by a combined analysis of BRCA1 and BRCA2 in Kaplan‐Meier analysis with RRBSO having a HR for ovarian/peritoneal cancer of 0.029 (95% CI = 0.009‐0.100, P < .001)." (PMID 33152107, 2021). "One study showed an annual risk of peritoneal cancer after RRSO of 0.20% for women with BRCA1 and 0.10% for women with BRCA2, and in another study there was a 20-year cumulative risk of peritoneal cancer of 3.5%." (PMID 31888263, 2019). "Pathogenic germline BRCA1, BRCA2 (BRCA1/2), and several other gene variants predispose women to primary ovarian, fallopian tube, and peritoneal carcinoma (OC), although variant frequency and relevance information is scarce in Japanese women with OC." (PMID 29348823, 2017). "Alsop and colleagues analyzed a series of 152 patients with peritoneal cancer and 40 with fallopian tube cancer and identified a total of 15.8% and 20% patients carrying a BRCA1/BRCA2 mutation, respectively." (PMID 27532258, 2016). "The risk of primary peritoneal carcinoma is also increased in patients carrying BRCA1 (and BRCA2) mutations with a cumulative lifetime risk of between 1.3–20%." (PMID 17850658, 2007). "Germline variants occurring in BRCA1 and BRCA2 give rise to hereditary breast and ovarian cancer (HBOC) syndrome, predisposing to breast, ovarian, fallopian tube, and peritoneal cancers marked by elevated incidences of genomic aberrations that correspond to poor prognoses." (PMID 38397209, 2024). "BRCA1 and BRCA2 proteins are concordantly expressed in sporadic ovarian and peritoneal carcinomas." (PMID 19602291, 2009). "Expected annual rates of ovarian/peritoneal cancer were 1% for BRCA1 ≥ 35 years and 0.5% for BRCA2 ≥ 45 years." (PMID 33152107, 2021). "For the primary disease site, the proportion of fallopian tube and peritoneal cancer was significantly higher in BRCA2+ (40.5%) compared with BRCA1+ (15.4%) and BRCA- (no pathogenic variant, 12.8%)." (PMID 33531027, 2021).
sarcoma (35 papers, 2010 to 2025). A usually aggressive malignant neoplasm of the soft tissue or bone. "A prior study found that the expression of PARP1, γH2AX, BRCA1, and BRCA2 was associated with shorter survival of patients with sarcoma." (PMID 40563612, 2025). "Recently, uterine leiomyosarcomas, a sarcoma subtype, have emerged as candidates for characterization by homologous recombination repair defects and BRCA-2 loss." (PMID 39768800, 2024). "Rearrangements affecting the BRCA2 gene have also been reported in breast/sarcoma families, causing a Li–Fraumeni type of cancer pattern." (PMID 22691290, 2012). "In our analysis, across sarcoma histotypes, BRCA2 was found to be the most commonly altered HR-/DDR-gene." (PMID 38716772, 2024). "BRCA1/2 mutations are well‐known causes of HRD, 4 and 22% of sarcoma patients carry mutations in BRCA1 and BRCA2, respectively." (PMID 36779660, 2023). "They report that BRCA2 and FANC genes are the most frequently mutated HR genes in sarcomas and find that a high HRD score is associated with HR gene mutations, increased HR gene expression and CIN." (PMID 36929572, 2023). "Further, in the U20S human sarcoma cell line, siRNA knockdown of BRCA2 induced a 4.6-fold sensitization to colony growth inhibition by both vosaroxin and doxorubicin." (PMID 21317456, 2010). "Mutations in the HR genes BRCA1 and BRCA2 and mutational signatures of BRCA deficiency were previously identified in soft tissue and bone sarcoma patients, which provided the first indication of HRDness in sarcomas." (PMID 36929572, 2023). "In striking contrast to BRCA1, BRCA2 alterations were found in 22% sarcoma." (PMID 36779660, 2023). "Interestingly, the four homozygous deletions over BRCA2 included two sarcomas, a cancer type not previously linked to BRCA2 mutations." (PMID 29089486, 2017). "A recent study investigated the molecular profiling of ped/AYA sarcomas and noted alterations in several DDR genes, including SLFN11, EWSR1, BRCA1, BRCA2, and MLH1." (PMID 40563612, 2025). "56.6% of all analyzed sarcoma samples carried alterations in HRR pathway genes; BRCA2, FANCA, and ATM were found among the top altered genes in 11, 10, and 8% of all cases, respectively." (PMID 36779660, 2023). "BRCA2 was mutated in 5 HS/CB (26%) and none in LS of mixed cancer types (TNBC, Merkel cell carcinoma, HGSC, MM, sarcoma, and basal cell carcinoma)." (PMID 34446728, 2021). "Four genes (BRCA2, CDK12, MLL2, and VHL) were differentially mutated (p-value < 0.05) between renal cell carcinoma patients and sarcoma patients; however, these differences were not significant when correcting for multiple comparisons (FDR q-values >0.5)." (PMID 29383146, 2017). "In addition, 33 novel gene fusions involving RB1, BCL2, and BRCA2 were identified in 21 patients, predominantly in genomically complex and other sarcomas, not in TRS." (PMID 40755265, 2025).
sarcoma (continued). "The 33 novel fusions were identified in 21 patients involving RB1, BCL2, and BRCA2; none were identified in patients with TRS, and 21 (21.0%) were identified in patients with genomically complex and other sarcomas (p < 0.001)." (PMID 40755265, 2025).
cervical carcinoma (34 papers, 2006 to 2026). A carcinoma arising from either the exocervical squamous epithelium or the endocervical glandular epithelium. "Olaparib is a PARPi that was initially approved for the treatment of breast and cervical cancers with BRCA1 or BRCA2 functional deficiencies, inducing a synthetic lethality effect." (PMID 38270643, 2024). "The P/LP variants in BRCA1 (OR, 4.92; 95% CI, 1.22-14.68; P = .01) and BRCA2 (OR, 4.46; 95% CI, 1.11-13.14; P = .02) were associated with cervical cancer." (PMID 37523182, 2023). "One patient developed cervical cancer, and another was diagnosed with metastatic renal cell tumour, both had a BRCA2 mutation." (PMID 35892866, 2022). "An investigative group which performed theranostic evaluation of cervical cancer specimens demonstrated that 21% of tumors had BRCA2 mutations and 10% had BRCA1 mutations." (PMID 36330376, 2022). "In this study, we showed that BRCA1 and BRCA2 overexpression in patients with advanced cervical cancer is associated with treatment failure." (PMID 24708616, 2014). "Interestingly, that study proposed a significant association of pathogenic variants in BRCA1 or BRCA2 with cervical cancer (BRCA1: OR, 4.92; p = .01; BRCA2: OR, 4.46; p = .02) compared with an East Asian reference population in gnomAD." (PMID 39440754, 2025). "Documentation of frequent mutations in BRCA1 and BRCA2 as well as in vitro efficacy against cervical cancer cells grants biological plausibility to the targeted treatment of cervical cancer with PARP-inhibitors, as well as for routine tumor genomic assessment of cervical cancer specimens." (PMID 36330376, 2022). "In the present study, we corroborated the potential impacts of BRCA1/2 pathogenic variants or VUS in other cancers and detected two hepatocellular carcinoma patients carrying BRCA2 variants (c.7409dup and c.4307T>C) and one cervical cancer patient harboring BRCA1 c.4801A>T." (PMID 32879886, 2020). "Notably, there is limited knowledge of BRCA2 mutational status in cervical cancer, and current literature focuses on germline mutations and its role on non-HPV related cervical cancers, mostly associated with hereditary syndromes." (PMID 30760827, 2019). "This study aims to comprehensively characterize the BRCA2 transcriptional landscape in breast, ovarian, and cervical cancers using a hybrid sequencing approach." (PMID 40640493, 2025). "The highest HRDsum score was in the cervical cancer cell line DOTC24510, which is homozygous for a stop-gain variant in BRCA2." (PMID 39485057, 2024). "BRCA2 was ranked top one and emerging evidence have demonstrated that BRCA2 plays an important role in cervical cancer." (PMID 37845756, 2023). "Genes with known or likely deleterious variants among cervical cancer patients with DDR gene alterations were ATM (n = 3, 2.33%), BRCA2 (n = 3, 2.33%), ATR (n = 2, 1.55%), CHEK2 (n = 2, 1.55%), followed by BRCA1 (n = 1, 0.78%), FANCA (n = 1, 0.78%), MSH6 (n = 1, 0.78%), and RAD51D (n = 1, 0.78%)." (PMID 35071000, 2021). "Although there are some targeted drugs that may be effective for cervical cancer, such as PARP inhibitors (for BRCA1 or BRCA2 mutations patients), EGFR tyrosine kinase inhibitors (for EGFR mutations patients), gene detection is still not widely used in China." (PMID 32265980, 2020). "These previous findings and the results of the present analysis suggest that TTK, AURKA and BRCA2 may participate in the progression of cervical cancer." (PMID 25695263, 2015). "There are no functional studies about BRCA2 mutation in cervical cancer." (PMID 30760827, 2019).
cervical carcinoma (continued). "For this purpose, T47D (BC cell line, BRCA1 and BRCA2 wt., HRP) and HeLa cells (cervical cancer cell line, BRCA1 and BRCA2 wt., HRP) were treated with a combination of curcumin (10, 20, and 30 μM) and the PARPi olaparib (0.1 and 0.25 μM)." (PMID 40647408, 2025). "In total, 28 genes (e.g., ATF2, BRCA2, CSRP2BP and EP300) were up-regulated and 16 genes (e.g., CDY1, CHAT and CRAT) were down-regulated in cervical cancer." (PMID 37845756, 2023). "Interestingly, the pathogenic p.W2830* BRCA2 mutation identified in HCB-514 has been identified in other cancers as a predictive marker for targeted therapies, such as PARP inhibitors; its role in cervical cancers remains unclear." (PMID 30760827, 2019). "In addition, we also found that the risks for liver and cervical cancers in female relatives of BRCA1 carriers, and lymphoma and kidney cancer in female relatives of BRCA2 carriers were significantly increased compared with female relatives of non-carriers." (PMID 36861435, 2023). "In cervical cancer cells, downregulation of WTIP abolished BRCA2-mediated centrosome localization and resulted in abnormal cell division, suggesting that WTIP might be involved in the development of cervical cancer." (PMID 34930905, 2021). "DNA repair pathway genes, such as BRCA1, BRCA2 and ATM, which are potential predictive biomarkers, also had a high frequency of CNVs in the present study, suggesting that HR defect might serve as a therapeutic target in cervical cancer." (PMID 35205332, 2022). "The overexpression of BRCA1, BRCA2, RAD51, BRIP1 (BACH1), FANCD2, BLM and RFC in non-responding versus responding cervical cancer samples suggests that DNA repair mechanism activation occurs through cell cycle arrest and homologous recombination." (PMID 24708616, 2014).
medulloblastoma (33 papers, 2010 to 2026). A malignant, invasive embryonal neoplasm arising from the cerebellum. "In Fanconi anemia group D1 patients with biallelic pathogenic GVs in BRCA2, brain tumors, particularly medulloblastoma and astrocytoma, were found in the first decade of life in almost half (15/27) of the cases, and glioblastoma in childhood was also reported." (PMID 41546701, 2026). "Tumor cells upregulate G4-resolving helicases to facilitate rapid proliferation through G4s highlighting PIF1 helicase as a potential therapeutic target for treatment of BRCA2-deficient medulloblastomas." (PMID 40854122, 2025). "This study highlights a specific source of endogenous DNA replication stress, G-quadruplexes (G4s), that can increase genome instability in BRCA2-deficient cerebellar granule cell progenitors (GCPs), leading to medulloblastoma." (PMID 40854122, 2025). "MB arising from BRCA2 deficiency was previously modeled in mice with nervous system-wide Brca2 mutation targeted to exon 11 that affected cerebellar development and led to medulloblastoma formation." (PMID 40854122, 2025). "Here, we present genetic, clinical, pathological and treatment characteristics observed in an international cohort of eight patients with FA due to biallelic BRCA2 pathogenic variants and medulloblastoma (MB), an embryonal tumor of the cerebellum." (PMID 38685107, 2024). "Numerous studies have proven the critical roles of genetic mutations, such as BRCA2 DNA Repair Associated (BRCA2), in the tumorigenesis of medulloblastoma." (PMID 38273337, 2024). "Medulloblastoma (MB) has been described only in few cases of FA with biallelic inactivation in the tumor suppressor gene BRCA2/FANCD1 or its associated gene PALB2/FANCN." (PMID 26064523, 2015). "Here, we report for the first time on a child carrying a familial heterozygous BRCA2 6174delT germline mutation, who presented with metastatic medulloblastoma." (PMID 26380221, 2015). "Notably, V66-exatecan demonstrated the ability to cross the BBB, effectively targeting BRCA1- and BRCA2-deficient autochthonous medulloblastomas." (PMID 41077566, 2025). "An example of a study supporting such causality showed that heterozygous pathogenic germline variants in PALB2 and BRCA2 in children with medulloblastoma had somatic mutational signatures typical of PALB2/BRCA2-related homologous recombination repair deficiency in the corresponding tumors." (PMID 34061292, 2021). "Targeting PIF1 may represent a therapeutic strategy for BRCA2-deficient medulloblastomas." (PMID 40854122, 2025). "Under those conditions, BRCA2 plays an integral role in preventing genomic instability at G4s in GCPs, averting medulloblastoma development." (PMID 40854122, 2025). "Brain tumors (mostly medulloblastoma), Wilms tumor, and neuroblastoma are almost exclusively seen in patients with FANCD1/BRCA2 and FANCN/PALB2 variants." (PMID 40970532, 2025).